MED25 (mediator complex subunit 25)
Description:
Component of the Mediator complex, a coactivator involved in the regulated transcription of nearly all RNA polymerase II-dependent genes. Mediator functions as a bridge to convey information from gene-specific regulatory proteins to the basal RNA polymerase II transcription machinery. Mediator is recruited to promoters by direct interactions with regulatory proteins and serves as a scaffold for the assembly of a functional preinitiation complex with RNA polymerase II and the general transcription factors. Required for RARA/RXRA-mediated transcription.
Synonyms: ARC92; ACID1; PTOV2; TCBAP0758; DKFZp434K0512; BVSYS; CMT2B2; P78
Tractability: Small molecule: a structure with a bound ligand is known. PROTAC: ubiquitination databases record sites on it; its protein half-life has been measured; a small molecule that binds it is known.
Gene: Protein-coding gene on chromosome 19 (49,818,277 to 49,840,383, forward strand). Ensembl gene ENSG00000104973.
Subcellular location: Nucleus
Subcellular location (Human Protein Atlas): Nucleoplasm
Pathways (Reactome):
Developmental Biology: Transcriptional regulation of white adipocyte differentiation
Disease: RSV-host interactions
Gene expression (Transcription): Generic Transcription Pathway
Metabolism: PPARA activates gene expression
Gene Ontology:
Molecular function: nuclear retinoic acid receptor binding; nuclear retinoid X receptor binding; protein binding; transcription coactivator binding
Biological process: negative regulation of fibroblast proliferation; negative regulation of transcription by RNA polymerase II; positive regulation of chromatin binding; positive regulation of mediator complex assembly; positive regulation of transcription by RNA polymerase II; positive regulation of transcription elongation by RNA polymerase II; positive regulation of transcription initiation by RNA polymerase II; RNA polymerase II preinitiation complex assembly
Cellular component: core mediator complex; nucleoplasm; nucleus; transcription regulator complex
Genetic constraint (gnomAD): Loss-of-function variants: 60 observed, 85.11 expected, observed/expected ratio (o/e) 0.7, 90% interval 0.57 to 0.87. The upper end of that interval is the gene's LOEUF score, 0.87, which puts it in group 3 of 6, group 1 being the genes least tolerant of losing a copy. Missense variants: 902 observed, 1,013.8 expected, observed/expected ratio (o/e) 0.89, 90% interval 0.84 to 0.94. Synonymous variants: 448 observed, 430.35 expected, observed/expected ratio (o/e) 1.04, 90% interval 0.96 to 1.13.
Gene-disease validity (ClinGen):
ClinGen rates the evidence that MED25 causes each of these diseases.
Charcot-Marie-Tooth disease type 2B2 (autosomal recessive): Disputed. Charcot-Marie-Tooth disease, type 2B2 (CMT2B2, also referred to as CMT4C3) is an axonal CMT peripheral sensorimotor polyneuropathy that has been described in a large consanguineous Costa Rican family of Spanish ancestry.
Homologues: Orthologues: chimpanzee MED25 (99% identical), dog MED25 (97% identical), macaque MED25 (95% identical), pig MED25 (92% identical), rat Med25 (91% identical), guinea pig MED25 (91% identical), mouse Med25 (89% identical), rabbit MED25 (79% identical), tropical clawed frog med25 (68% identical), zebrafish med25 (54% identical), Drosophila melanogaster MED25 (28% identical), Drosophila melanogaster CG13609 (10% identical). Paralogues in human: PTOV1 (22% identical).
Diseases named in the same sentence as MED25 in open-access papers:
MED25 is named in the same sentence as 28 diseases in open-access papers, as found by Europe PMC text mining. Sharing a sentence is not in itself a finding about the gene and the disease. The quoted sentences say what the papers report.
Intellectual disability (4 papers, 2018 to 2025). "The variant c.418C > T (p.A140T) in MED25 was reported to be related to intellectual disability (ID)." (PMID 40909439, 2025). "Mutations in MED25 have been linked to various genetic syndromes, including Basel-Vanagaite-Smirin-Yosef Syndrome (BVSYS) and Intellectual Disability (ID)." (PMID 40909439, 2025). "Mutations in MED25 are associated with Basel-Vanagaite-Smirin-Yosef Syndrome (BVSYS) and Intellectual disability (ID)." (PMID 40909439, 2025). "Consequently, other autosomal recessive intellectual disability genes have been also described in this same population, such as MED25." (PMID 37508980, 2023). "In this case, the clinical features of the proband were only cognitive-linguistic intellectual disability and microcephaly, and lacked other typical clinical features of BVSYS caused by MED25 mutations." (PMID 40909439, 2025).
Basel-Vanagaite-Smirin-Yosef Syndrome (2 papers, 2022 to 2025). "Moreover, the MED25 gene is associated with Basel-Vanagaite-Smirin-Yosef syndrome, which is an autosomal recessive inheritance." (PMID 40909439, 2025).
microcephaly (2 papers, 2025). A congenital or acquired developmental disorder in which the circumference of the head is smaller than normal for the person's age and sex. "Patients with MED25 biallelic variants have microcephaly, congenital cataract, and severe developmental delay, yet lack cerebellar and pontine changes." (PMID 40745490, 2025).
MODY (2 papers, 2012 to 2025). "Mutations at the HNF4α binding site of MED25 are often associated with MODY, underscoring the role of MED25 in the HNF4α-mediated insulin secretion and associated diabetes." (PMID 40940746, 2025). "Here we report the identification of MED25 as one of the HNF4α binding partners in pancreatic ß-cells leading to insulin secretion which is impaired in MODY patients." (PMID 22952853, 2012).
Sepsis (2 papers, 2020 to 2023). Sepsis is defined as life-threatening organ dysfunction caused by a dysregulated host response to infection. "CD247, DOCK2, IFI35, ITK, LCK, and MED25 might be important targets affecting the prognosis of sepsis." (PMID 33015708, 2020). "Overall, through mouse study and online patient data analysis, five genes (CD247, DOCK2, IFI35, ITK, and LCK) were reported to positively correlate with sepsis prognosis whilst only the expression of MED25 displayed a negative correlation." (PMID 37456011, 2023). "Sepsis development/progression in mice could be regulated by changing the LPS amount, as an example of using different doses of LPS to set survival and death groups in the discovery of six genes (CD247, DOCK2, IFI35, ITK, LCK and MED25)." (PMID 37456011, 2023).
viral infections (2 papers, 2020 to 2024). "Whereas MED18 is considered a susceptibility factor, MED25 is required for defense against virus infection." (PMID 38245701, 2024). "In contrast, med25 mutants were susceptible to all viral infections which suggest that MED25-mediated gene expression is required for plant defense signaling against viruses and further studies may reveal whether MED25 is also needed to interfere with viral mechanisms that inhibit RNA silencing." (PMID 32194589, 2020). "MED18 is required for normal virus infection, while MED25 is important for defense against virus infection." (PMID 32194589, 2020). "Defense marker gene expression profiling of mock- and virus-inoculated plants showed that med18 and med25 mutants exhibited an upregulated SA pathway upon virus infection at 2 dpi for all viruses tested." (PMID 32194589, 2020). "This study can help to understand how plants interact with viruses and assist in establishing the pathways, including the roles of Mediator subunits MED18 and MED25, that were found to be required for normal virus infection and defense against viruses, respectively." (PMID 32194589, 2020). "Interestingly, med25, showed increased susceptibility to all viruses tested, suggesting that this Tail-located subunit plays a role in antivirus defense signaling (rather than normal virus infection)." (PMID 32194589, 2020).
axonal peripheral neuropathy (1 paper, 2018). "In conclusion, we provide evidence that PNKP is the main gene related to CMT2B2 instead of MED25, and that it should be considered as a gene involved in an axonal peripheral neuropathy with late age onset, cerebellar atrophy, and with or without oculomotor apraxia." (PMID 30039206, 2018).
cardiomyopathy (1 paper, 2023). A disease of the heart muscle or myocardium proper. "We previously identified Med25 in a translatome screen of adult cardiomyocytes (CMs) in a novel cell type-specific model of LMNA cardiomyopathy." (PMID 37047128, 2023).
Charcot-Marie-Tooth disease (1 paper, 2018). An inherited degenerative disorder involving the peripheral nerves. "Also, we showed that in mice and rats Med25 is coordinately expressed with Pmp22 gene, a gene involved in the Charcot-Marie-Tooth disease." (PMID 30039206, 2018).
hereditary spastic paraplegia (1 paper, 2017). Hereditary spastic paraplegias (HSP) comprise a genetically and clinically heterogeneous group of neurodegenerative disorders characterized by progressive spasticity and hyperreflexia of the lower limbs. "Of note, there are nine genes among these targets that when mutated are known causes for inherited peripheral neuropathies (IPN) and hereditary spastic paraplegia (HSP) (Inf2, Sox10, Wnk1, Med25, Fa2h, Bscl2, Slc12a6, Kif1a and Kif5a)." (PMID 28077174, 2017).
Infertility (1 paper, 2021). "MED25 was previously shown to play a critical role in the endoplasmic reticulum stress response Here, a number of the DEPs identified in the current work, including TSPAN8, SUMO3, INSL3, and MED25, were implicated in obesity-related infertility or subfertility." (PMID 34016141, 2021).
intellectual disability syndrome (1 paper, 2025). "Common to these sets of m6A and m5C effector proteins were the proteins MED23 and MED25 which cause AR ID, syndromic ID and eye–intellectual disability syndrome and which are components of the mediator complex which repress transcription by RNA polymerase II." (PMID 39499421, 2025).
lymphoma (1 paper, 2024). A malignant (clonal) proliferation of B- lymphocytes or T- lymphocytes which involves the lymph nodes, bone marrow and/or extranodal sites. "Interestingly, MED25 was commonly identified in both nTFHL and nPTCL, pointing to a possible unexplored role of this transcription factor in both lymphoma subtypes." (PMID 38291429, 2024).
infection (6 papers, 2016 to 2025). The state of being infected such as from the introduction of a foreign agent such as serum, vaccine, antigenic substance or organism. "Accordingly, induction of JMT, a MYC2 target gene encoding an S-adenosyl-L-methionine:JA carboxyl methyltransferase that catalyzes formation of MEJA from JA, was severely reduced in med16 and med25 due to a combination of elevated levels before, and deficient induction after infection." (PMID 38514763, 2024). "In MED25-knockdown cells, rRSV-mCherry replication was further attenuated at a late post-infection timepoint." (PMID 40920851, 2025). "Mediator consists of a complex of transcriptional coactivators, suggesting that NS1 targets MED25 to disturb host transcription and to reshape the host immune response to infection." (PMID 36102648, 2022). "Infection with all viruses exhibited clear growth reduction in plants, with visible symptoms being strongest in med25 mutants and weakest in med18 mutants." (PMID 32194589, 2020). "MED25 may regulate macrophage gene expression in infection or inflammation by enhancing the recruitment of transcription factors or stabilizing pre-transcriptional initiation complexes." (PMID 41584584, 2025). "Therefore, the interaction between RSV NS1 and cellular MED25 might be beneficial for RSV during infection by affecting host transcription and the host immune response to infection." (PMID 36102648, 2022). "In A549 cells depleted of MED25, we observed that replication was attenuated for WT rRSV-mCherry as well as for NS1 mutants at a late timepoint post-infection." (PMID 40920851, 2025). "Mediator subunits MED8, MED15, MED16, MED18, MED20, MED25 and CDK8 were identified as important for diverse types of infection responses." (PMID 38514763, 2024). "Med25 mRNA was stably expressed in untreated and VZV-infected cells over the first 24 h after infection." (PMID 26985360, 2016). "Interestingly, after infection of A549 cells with RSV NS1-BirA*-Flag, we could coimmunoprecipitate endogenous MED25 with NS1-BirA*." (PMID 36102648, 2022).
Neurological Disease (2 papers, 2015 to 2025). "The search identified the protein MED25, which is linked to human diseases including neurological disorders, with a 7-aa sequence (PPGAPKP, which is conserved in EV71) match with EV71 VP1." (PMID 25826188, 2015).
genetic diseases (1 paper, 2025). "Currently, several different site mutations on the MED25 gene have been reported to be associated with genetic diseases." (PMID 40909439, 2025).
peripheral neuropathies (1 paper, 2018). "In our previous study, we demonstrated that in rats Med25 expression correlated with Pmp22 dosage and expression, which is interesting because Pmp22 is a gene involved in demyelinating peripheral neuropathies." (PMID 30039206, 2018).
MED25 also shares sentences with these, for which no sentence is quoted: Ataxia (1 paper); Cerebellar atrophy (1); Cerebro-oculo-facio-skeletal syndrome (1); cleft palate (1); developmental delay (1); diabetes (1); hereditary motor and sensory neuropathy (1); neuropathy (1); Obesity (1); varicella (1); zoster (1).